TP63 (tumor protein p63)
Diseases named in the same sentence as TP63 in open-access papers (continued):
Sharing a sentence is not in itself a finding about the gene and the disease.
lung squamous cell carcinoma (13 papers, 2015 to 2024). "Variation in TP63 is associated with drivers of squamous cell lung cancer." (PMID 29697361, 2018). "Study of the TCGA data corroborates that both HRAS and TP63 expression are significantly elevated in advanced stage HNSCCs and early-stage lung squamous cell carcinoma (LSCC) compared to normal tissue." (PMID 37638000, 2023). "Recently, SOX2 and TP63 were shown to interact functionally and co-localize to a large number of genomic binding sites in squamous cell lung cancer." (PMID 25994056, 2015). "Positive staining for Keratin 5, Keratin 6, Keratin 14, or TP63 can indicate squamous cell carcinomas of the lung." (PMID 25955027, 2015). "ΔNp63α (TP63) mRNA levels positively correlated with NRF2 (NFE2L2) mRNA levels in ESCA and lung squamous cell carcinoma (LUSC)." (PMID 39500864, 2024). "Exosomal TP63, KRT5, CEACAM6, and SFTPB mRNAs can be used as biomarkers to differentiate between lung squamous cell carcinoma (LUSC) and lung squamous cell carcinoma (LUAD), thereby, providing a novel strategy for their differential diagnosis and treatment." (PMID 35584089, 2022). "Two of the four TFs we identified in squamous cell lung cancer (LUSC), TP63 and SOX2, are oncogenes that are overexpressed in LUSC through genomic amplification." (PMID 25994056, 2015).
limb-mammary syndrome (12 papers, 2016 to 2025). Limb-mammary syndrome (LMS) is a rare disease belonging to the group of ectodermal dysplasias. "Point mutations in the TP63 gene result in distinct syndromes: ectodermal dysplasia (ED) syndromes, which are ectrodactyly ectodermal dysplasia cleft lip/palate (EEC), ankyloblepharon–ectodermal dysplasia clefting (AEC), acro–dermato–ungual–lacrimal–tooth (ADULT), and limb–mammary syndrome (LMS)." (PMID 39791744, 2025).
cleft lip (11 papers, 2012 to 2025). Congenital defect in the upper lip where the maxillary prominence fails to merge with the merged medial nasal prominences. "Two heterozygous missense variants in TP63 were identified in individuals from two unrelated families, Family 3 and Family 9, who presented with bilateral cleft lip and palate (CLP), ectrodactyly, and other orofacial and limb malformations." (PMID 41510282, 2025). "And our study also provides clinical evidence for the molecular mechanism of TP63 gene causing nonsyndromic cleft lip with or without cleft palate (NSCL/P)." (PMID 33622322, 2021). "Incomplete penetrance in cleft lip and palate (CLP) exemplifies the phenomenon where individuals carrying mutations in specific genes, such as IRF6, MSX1, and TP63, do not consistently express the associated phenotype." (PMID 39506048, 2025).
cleft palate (9 papers, 2010 to 2025). Cleft palate is a fissure type embryopathy that affects the soft and hard palate to varying degrees. "TP63 is associated with cleft palate in Tp63 deficient mice, which is associated with an increased prevalence of OSA, suggesting that its relationship to OSA may be through pathways influencing craniofacial development." (PMID 34446064, 2021). "We selected eight genes associated with cleft palate (i.e., fibroblast growth factor receptor (FGFR), epidermal growth factor (EGF), PAX9, and tumor protein p63 (TP63))." (PMID 31480549, 2019).
pancreatic cancer (9 papers, 2018 to 2022). "Publicly available datasets revealed a positive correlation between KRT14 and TP63 in lung, cervix, oesophagus and pancreatic tumours." (PMID 32128997, 2020).
prostate carcinoma (9 papers, 2011 to 2024). A carcinoma that arises from epithelial cells of the prostate gland. "NKX2-5, RUNX1, TRPS1, FOXO1, and TP63 play a inhibitory roles in the development of prostate cancer." (PMID 38778150, 2024). "The process of the RTK/RAS pathway driving prostate cancer lineage plasticity is a complex interplay involving multiple TFs, with TP63, FOXO1, and RORC potentially playing more crucial roles due to their relatively high activity levels." (PMID 38778150, 2024). "The transcriptional activities of NKX2-5, RUNX1, TRPS1, FOXO1, and TP63 are negatively correlated with LEGs, suggesting these suppress prostate cancer lineage plasticity through the RTK/RAS pathway." (PMID 38778150, 2024). "Genes typically associated with prostate cancer are evident: PCA3 and GDF15 levels are elevated, and TP63 and MSMB levels are reduced across all tumour subgroups, and are not subtype-specific." (PMID 26501111, 2015). "In one recently described model, cell fractionation studies of CWR22 human prostate cancer xenograft tumors demonstrated that tumor protospheres containing CK8+/CK5+/AR-/TP63- cells gave rise to CK8+/CK5-/AR+ tumors." (PMID 22022528, 2011). "TP63 has a lower expression in prostate cancer cells compared to normal prostate cells, indicating that it may serve as a key molecule in fight against prostate cancer." (PMID 36105400, 2022). "Particularly, TFs TP63 and FOXO1 suppress and RORC drives prostate cancer lineage plasticity through the RTK/RAS pathway." (PMID 38778150, 2024). "In the transcriptional regulation network, TP63 and FOXO1 act as suppressors of prostate cancer lineage plasticity, whereas RORC exerts a promoting effect." (PMID 38778150, 2024). "Based on all the information presented above, TP63 and FOXO1 suppress prostate cancer lineage plasticity through the RTK/RAS pathway, whereas RORC drives prostate cancer lineage plasticity through RTK/RAS pathway." (PMID 38778150, 2024). "The CNVs and TFs, such as TP63, FOXO1, and RORC, promote the RTK/RAS pathway-driven prostate cancer lineage plasticity by upregulating the LEGs." (PMID 38778150, 2024). "To investigate the pyroptosis pattern in prostate cancer at the single-cell level, we used previously defined Class Markers (CHMP4C and TP63) to re-assign each malignant epithelial cell to Class1, Class2 or Not Defined." (PMID 36105400, 2022). "To validate these two classifier genes in human cell lines, we studied the distribution and expression of TP63 and the relative mRNA expression level of CHMP4C and TP63 in normal prostate cell line RWPE-1 and prostate cancer cell line DU-145." (PMID 36105400, 2022). "TP63 and FOXO1 inhibit prostate cancer lineage plasticity and RORC promotes it." (PMID 38778150, 2024).
diffuse large B-cell lymphoma (7 papers, 2015 to 2024). "Latest study showed that a novel translocation between programmed cell death ligand 1 (PD-L1) (cluster of differentiation 274) and TP63 (tumor protein 63) can be found in diffuse large B-cell lymphoma (DLBCL), resulting in their conjunct overexpression in tumor cells at RNA level." (PMID 28403071, 2017). "The newly identified TBL1XR1/TP63 gene fusion was discovered using transcriptome sequencing in diffuse large B-cell lymphoma (DLBCL)." (PMID 38347836, 2024).
lymphoma (7 papers, 2015 to 2022). A malignant (clonal) proliferation of B- lymphocytes or T- lymphocytes which involves the lymph nodes, bone marrow and/or extranodal sites. "In DLBCL cell lines, FOXP1, directly represses TP63 and cooperate with NF-κB signaling to promote lymphoma cell survival." (PMID 26878872, 2016). "Immunohistochemistry for p63 is not specific for a TP63 rearrangement but it is a useful screening test to select cases of ALK- ALCL for TP63 FISH, particularly in cases with >30% positive lymphoma cells." (PMID 34572893, 2021). "Taken together that hepatitis seropositivity is associated with DLBCL, CLL and MZL risk and that AICDA promiscuous off-target activity, highly present in lymphomas and induced by viral infection, can provoke important alterations (example translocations of PD-L1/PD-L2 with PIM1, TP63, and IGH loci)." (PMID 33374413, 2020).
psoriasis (7 papers, 2015 to 2025). An autoimmune condition characterized by red, well-delineated plaques with silvery scales that are usually on the extensor surfaces and scalp. "TP63 is an essential TF for skin homeostasis, has been implicated in psoriasis and is mis-expressed in this condition." (PMID 40998781, 2025). "Regarding the relationship between TP63 and noncancer human diseases, a genome-wide meta-analysis revealed that TP63 is associated with psoriasis." (PMID 37212280, 2023). "The discovery of TP63 as a novel susceptibility locus provides additional biological insight into the role of keratinocyte proliferation and differentiation in the development of psoriasis." (PMID 25903422, 2015). "In the present study, KRT6, IL‐17 and IL‐22 protein within psoriasis lesions was decreased, while KRT10 and Tp63 protein in psoriasis lesions was increased by ozone treatment in both patient and IMQ mice psoriatic tissues." (PMID 32168425, 2020). "A role for TP63 in the development or maintenance of psoriasis is supported by the fact that ΤP63 expression appears to be involved in epidermal remodeling, even in the early stages of the disease and TP63 major isoform is differentially regulated in psoriasis." (PMID 41153404, 2025). "This work evaluated the expression levels of the circulating miR-203 target genes SOCS3, SOCS6, TP63, TNF-, IL8, and IL24 in psoriasis patients." (PMID 36341243, 2022). "In order to gain a better knowledge of miRNAs role in the disease, the current study looked into the influence of miR-203 expression and its target genes SOCS3, SOCS6, TP63, TNF-α, IL-8, and IL-24 on the pathogenesis and clinical course of psoriasis." (PMID 36341243, 2022). "As a further confirmation, Tp63 mRNA and KRT10 mRNA expression were significantly up‐regulated in ozone‐treated psoriasis lesions; Tp63 and KRT10 mRNA expression in tissue samples was positively correlated." (PMID 32168425, 2020). "Tp63 and KRT10 mRNA expression could be remarkably up‐regulated upon ozone treatment in psoriasis lesions, compared to those in non‐treated psoriasis lesions." (PMID 32168425, 2020). "In conclusion, the application of ozonated oil could be an efficient and safe treatment for psoriasis; ozone promotes the differentiation of keratinocytes via increasing Tp63‐mediated transcription of KRT10, therefore improving psoriasis." (PMID 32168425, 2020). "In conclusion, the application of ozonated oil could be an efficient and safe treatment for psoriasis; ozone promotes the differentiation of basal keratinocytes via increasing Tp63‐mediated transcription of KRT10, therefore improving psoriasis." (PMID 32168425, 2020). "Finally, the mRNA expression of Tp63 and KRT10 was examined in psoriasis lesion tissues with or without ozone treatment; we examined the interaction between the expression of Tp63 and KRT10 within tissues using Pearson's correlation analysis." (PMID 32168425, 2020). "The protein levels of Tp63 were remarkably down‐regulated in lesion tissues without ozone therapy, compared to those in normal skin tissues; ozone treatment increased the protein levels of Tp63 in psoriasis lesions." (PMID 32168425, 2020). "To provide further evidence, we examined Tp63 and KRT10 expression in psoriasis lesion tissues with or without ozone treatment." (PMID 32168425, 2020).
anaplastic large cell lymphoma (6 papers, 2017 to 2025). Anaplastic large cell lymphoma (ALCL) is a rare and aggressive peripheral T-cell non-Hodgkin lymphoma, belonging to the group of CD30-positive lymphoproliferative disorders, which affects lymph nodes and extranodal sites. "Anaplastic large cell lymphomas (ALCLs) represent a group of CD30-positive T-cell lymphomas that often contain chromosomal rearrangements in the ALK locus and, similar to PTCLs, may contain TP63 rearrangements which are generally associated with poor patient outcome." (PMID 39791744, 2025). "Rearrangement or extra copies of the TP63 gene were demonstrated in a subset of anaplastic large cell lymphoma but not in PMLBCL." (PMID 31831043, 2019).
glioma (6 papers, 2019 to 2025). A benign or malignant brain and spinal cord tumor that arises from glial cells (astrocytes, oligodendrocytes, ependymal cells). "Elevated β-catenin transcriptionally upregulates TP63, which in turn promotes GPX4 expression and suppresses lipid peroxidation and ROS accumulation, thereby facilitating glioma cell survival and resistance to ferroptotic cell death." (PMID 40796737, 2025). "MiRNA-21 exerts its oncogenic function in gliomas through its post-transcriptional targets and downstream signal pathways: PDCD4, phosphatase and tensin homolog (PTEN), tumour protein 63 (TP63), tropomyosin 1 (TPM1), and tissue inhibitor of metalloproteases 3 (TIMP3)." (PMID 33610185, 2021).
esophageal cancer (5 papers, 2012 to 2023). A primary or metastatic malignant neoplasm involving the esophagus. "Moreover, a strong positive correlation between TMTC3 and TP63 was confirmed in esophageal cancer (EC)." (PMID 35982901, 2022). "GSVA found that Tumor microenvironment, Epithelial cells, as well as Barrett's esophagus and esophagus cancer were significantly up-regulated in the high NCS group, while TP73 and TP63 targets, Response to metal ions, Response to THC were significantly downregulated." (PMID 37291676, 2023).
gastric cancer (5 papers, 2018 to 2024). A primary or metastatic malignant neoplasm involving the stomach. "For example, rs35592567 polymorphism affect the expression of TP63 by interfering miR-140, which may serve as a reasonable explanation for the increased susceptibility of gastric cancer." (PMID 29997452, 2018). "Interestingly, the IL10+ Treg cluster also expressed high levels of PTMS, ZNF282, and TP63, which have been associated with oncogene activity and might help explain the association of H. pylori infection with the development of gastric cancer." (PMID 36810249, 2023).
leukemia (5 papers, 2017 to 2022). A malignant (clonal) hematologic disorder, involving hematopoietic stem cells and characterized by the presence of primitive or atypical myeloid or lymphoid cells in the bone marrow and the blood. "In the current study, we aimed to explore the association of variant rs10937405 of TP63 with leukemia in the North Indian population of Jammu and Kashmir." (PMID 35222588, 2021). "In the present study, association of the variant rs10937405 of TP63 with leukemia was explored in the North Indian population." (PMID 35222588, 2021). "The variant rs10937405 of TP63 was found significantly associated with all four subtypes of the leukemia (p-value = 0.002, 0.0001, 0.032, and 0.034 for ALL, AML, CML, and CLL, respectively)." (PMID 35222588, 2021). "We observed that genetic allele T of variant rs10937405 of TP63 is significantly associated with leukemia (p value =1.2 × 10−6), with H.W. E = 0.974." (PMID 35222588, 2021). "Our findings provide evidence that the variant rs10937405 of TP63 is significantly association with leukemia in the population of Jammu and Kashmir in Northern India." (PMID 35222588, 2021). "The role of single nucleotide polymorphism rs10937405 (C>T) of the TP63 gene in cancer including leukemia has previously been studied in different world populations; however, the role of this variant in leukemia in the North Indian population of Jammu and Kashmir is still unknown." (PMID 35222588, 2021).
non-small cell lung carcinoma (5 papers, 2008 to 2025). A group of at least three distinct histological types of lung cancer, including non-small cell squamous cell carcinoma, adenocarcinoma, and large cell carcinoma. "The inhibition of miR-221 via GAS5 sponging has also been demonstrated to upregulate tumor protein p63 (TP63), a central tumor suppressor in non-small cell lung cancer (NSCLC)." (PMID 39941145, 2025). "Bioinformatic analyzes of our study revealed a significant correlation between TP63 expression and SLUG expression in non-small cell lung cancer samples, suggesting that the two proteins act together in the EMT process." (PMID 35201505, 2022). "Further, PDX tissue sections generally did not express antigens characteristic of non-small cell lung cancers, including Keratin 5, Keratin 6, Keratin 7, Keratin 14, Keratin 20, TTF1, TP63, and Napsin A." (PMID 25955027, 2015).
ovarian carcinoma (5 papers, 2015 to 2024). A malignant neoplasm originating from the surface ovarian epithelium. "Recent studies have shown that FZD7 could inhibit ferroptosis in ovarian cancer through β-catenin/TP63/GPX4 pathway." (PMID 37060074, 2023). "However, some PYAGs with CNV gain, such as GSDMD, TP63, PRKACA, PJVK and CASP4, showed downregulated mRNA expression in ovarian cancers, and some PYAGs with CNV loss, such as IL18, GPX4, GZMA, NLRP6 and CASP6, showed upregulated mRNA expression in ovarian cancers." (PMID 36707884, 2023).
skin cancer (5 papers, 2015 to 2025). "Mutations in the Hras, Pten, Pi3k, Mdm2, Tp63, Esr, Pgr, and Her2 genes, loss of Cdkn2a, Igf, and Akt, as well as MYC phosphorylation have been identified in DMBA-induced breast, blood, and skin tumor models." (PMID 41426972, 2025). "Overexpression or amplification of TP63 is observed in multiple cancer types generally from epithelial origin and p63 staining therefore serves as a classification biomarker in some malignancies including skin cancer." (PMID 36970727, 2022). "Thus, multiple signal pathways, such as BRAF, PI3K, and TP63/KLF5, can control SREBP-1 for the regulation of skin cancer progression." (PMID 35912181, 2022).